ANKRD30A (ankyrin repeat domain 30A)
Synonyms: NY-BR-1
Tractability: PROTAC: ubiquitination databases record sites on it.
Gene: Protein-coding gene on chromosome 10 (37,125,598 to 37,232,567, forward strand). Ensembl gene ENSG00000148513.
Subcellular location (Human Protein Atlas): Nucleoli
Pathways (Reactome):
Developmental Biology: Developmental Lineage of Mammary Gland Alveolar Cells; Developmental Lineage of Mammary Gland Luminal Epithelial Cells
Genetic constraint (gnomAD): Loss-of-function variants: 123 observed, 110.34 expected, observed/expected ratio (o/e) 1.11, 90% interval 0.96 to 1.29. The upper end of that interval is the gene's LOEUF score, 1.29, which puts it in group 5 of 6, group 1 being the genes least tolerant of losing a copy. Missense variants: 1,287 observed, 1,150.1 expected, observed/expected ratio (o/e) 1.12, 90% interval 1.07 to 1.17. Synonymous variants: 452 observed, 389.25 expected, observed/expected ratio (o/e) 1.16, 90% interval 1.07 to 1.25.
Homologues: Orthologues: chimpanzee ANKRD30A (89% identical), macaque ANKRD30A (62% identical), tropical clawed frog ankrd7 (15% identical), zebrafish si:ch211-272n13.3 (7% identical), Caenorhabditis elegans lem-3 (6% identical), Drosophila melanogaster CG8679 (6% identical), Caenorhabditis elegans F44E5.15 (3% identical), Drosophila melanogaster CG42391 (1% identical), Caenorhabditis elegans K07D4.2 (1% identical). Paralogues in human: ANKRD30B (70% identical), ANKRD26 (32% identical), ANKRD62 (22% identical), ANKRD20A1 (22% identical), ANKRD18B (18% identical), ANKRD18A (17% identical), ANKRD30BL (14% identical).
Diseases named in the same sentence as ANKRD30A in open-access papers:
ANKRD30A is named in the same sentence as 19 diseases in open-access papers, as found by Europe PMC text mining. Sharing a sentence is not in itself a finding about the gene and the disease. The quoted sentences say what the papers report.
breast cancer (17 papers, 2006 to 2025). A primary or metastatic malignant neoplasm involving the breast. "Association of ANP32E, DSC2, IL6ST and ANKRD30A mRNA expression with clinicopathological features in breast cancer cases from the second cohort." (PMID 35387118, 2022). "LncRNA CTD-3032H12.1 is predicted to interact with another lncRNA RP11-20F24.2 and mRNA of ANKRD30A, a transcription factor implicated in breast cancer progression, using a tissue-specific co-expression regulatory network model." (PMID 34946977, 2021). "ANKRD30A encodes for a breast differentiation antigen, NY-BR-1, which is often dysregulated in breast cancer and has been investigated as a general breast cancer biomarker previously." (PMID 33672646, 2021). "Similarly, the ANKRD30A encodes a DNA-binding transcription factor implicated in breast cancer." (PMID 33033484, 2020). "The cluster‐defined genes, PIP and ANKRD30A, were exclusively expressed in P8 CSF‐CTCs, indicating sufficient evidence to diagnose the primary site as breast cancer, sweat/salivary gland cancer, or prostate cancer." (PMID 33377642, 2020). "ANKRD30A is restricted to normal breast, normal testis, normal prostate and also detected in breast cancer as a breast cancer‐specific marker and in prostate cancer." (PMID 33377642, 2020).
HIV-1 infection (2 papers, 2015 to 2018). The type species of lentivirus and the etiologic agent of acquired immunodeficiency syndrome (AIDS). "Ankyrin repeat domain 30A (ANKRD30A) encodes a host factor for human immunodeficiency virus-1 (HIV-1) infection." (PMID 30079052, 2018). "ANKRD30A is a recently-discovered host factor for HIV-1 infection; however, little is known about the role of ANKRD30A in HIV biology." (PMID 25884674, 2015).
colorectal cancer (1 paper, 2023). A primary or metastatic malignant neoplasm that affects the colon or rectum. "Among the mutated genes in the adenomatous tissue samples involved in our study, PCDHGB4, AHRR, KIF4, LPAR6, NBPF1, and NCEH1 were already associated with colorectal cancer formation, while ANKRD30A, ITIH1, and KIAA0556 were related to other types of cancers." (PMID 36765865, 2023).
triple-negative breast carcinoma (1 paper, 2021). An invasive breast carcinoma which is negative for expression of estrogen receptor (ER), progesterone receptor (PR), and human epidermal growth factor receptor 2 (HER2). "Some differentiation antigens are overexpressed in particular biological contexts, such as breast tissue antigen Ankyrin repeat domain 30A (also known as NY-BR-1) whose expression is strongly correlated with estrogen-receptor status and is often low in triple-negative breast cancer." (PMID 34201655, 2021).
cancer (11 papers, 2007 to 2025). A tumor composed of atypical neoplastic, often pleomorphic cells that invade other tissues. "Of interest were the associations with ANKRD30A, SPTBN1, and GALNTL5, as these genes have known and well-defined cancer associations." (PMID 33672646, 2021). "Regarding PCAT5 and ANKRD30A, it is reported that both of them are related to cancer progression." (PMID 33033484, 2020). "As in the cancer cell lines, we observed promoter hypomethylation in the primary tumors; the frequency of hypomethylation was 5% (1/20) for ANKRD30A, 20% (4/20) for FLJ40201, 0% (0/20) for INSL6, 30% (6/20) for SOHLH2, 20% (4/20) for FTMT, 25% (5/20) for C12orf12, and 30% (6/20) for DPPA5." (PMID 17967063, 2007). "Genes such as MAGEA3 and MAGEA6 contributed targets for 7 cancer types each, while genes such as UMODL1, NLRP4, MAGEC2, ANKRD30A, and GPRC6A contributed targets for only 1 cancer type." (PMID 27439771, 2016).
tumor (9 papers, 2006 to 2023). "ANKRD30A expression was significantly associated with tumor size, ER, PR and TNBC status (p = 0.0161, 0.0007, 0.0009, 0.0012, respectively)." (PMID 35387118, 2022). "Previous studies from our laboratory have identified four genes (ANP32E, DSC2, ANKRD30A and IL6ST/gp130) that are specific to TNBC and were associated with lymph node metastasis (LNmets), the earliest indicator of tumor progression via distal spread." (PMID 35387118, 2022). "Thus, this implies that downregulation of ANKRD30A may have a significant role in tumor progression in TNBC." (PMID 35387118, 2022).
ANKRD30A also shares sentences with these, for which no sentence is quoted: melanoma (2 papers); adenoma (1); adrenal gland tumors (1); breast tumors (1); ductal carcinoma (1); ductal carcinoma in situ (1); invasive breast carcinoma (1); male breast carcinoma (1); mammary adenocarcinoma (1); metastatic carcinoma (1); prostate carcinoma (1); salivary gland cancer (1); thyroid adenocarcinoma (1).